INTS6P1 (integrator complex subunit 6 pseudogene 1)
Gene: Processed pseudogene on chromosome 5 (39,718,984 to 39,721,513, reverse strand). Ensembl gene ENSG00000250492.
Diseases named in the same sentence as INTS6P1 in open-access papers:
INTS6P1 is named in the same sentence as 4 diseases in open-access papers, as found by Europe PMC text mining. Sharing a sentence is not in itself a finding about the gene and the disease. The quoted sentences say what the papers report.
hepatocellular carcinoma (6 papers, 2015 to 2020). A malignant tumor that arises from hepatocytes. "Both INTS6 and pseudogene INTS6P1 play roles in repressing hepatocellular cancer by competing for onco‐miR‐17‐5p binding, which facilitates hepatocellular cancer initiation and progression." (PMID 27561207, 2017). "Analogously, pseudogene INTS6P1 expression is high and steady in normal people compared with hepatocellular carcinoma (HCC) patients." (PMID 27329719, 2016). "Researchers in another study found that they benefited from INTS6P1 in plasma when identifying and screening hepatocellular carcinoma (HCC)." (PMID 30337839, 2018).
tumor (3 papers, 2015 to 2020). "INTS6P1, a tumor suppressive pseudogene-derived lncRNA, exerted its roles in HCC by competitively binding to oncogenic miR-17-5p and thus upregulating its cognate gene INTS6." (PMID 32185172, 2020). "The current study, for the first time, strongly argues that INTS6P1 plays a tumor suppressive role in HCC by suppressing HCC cell growth, migration and survival." (PMID 25686840, 2015). "The current study reports, for the first time, that INTS6 and its pseudogene INTS6P1 are tumor suppressors in HCC." (PMID 25686840, 2015). "INTS6P1 upregulated its cognate gene INTS6 through competitively binding to miR-17-5p, thereby functioning its tumor suppressive roles in HCC." (PMID 32185172, 2020). "Taken together, these findings suggest that INTS6P1 and INTS6 exert tumor suppressive effects by promoting HCC cell death and inhibiting cell mobility." (PMID 25686840, 2015). "Taken together, these findings demonstrate INTS6P1 and INTS6 exert the tumor suppressive roles through competing for oncomiR-17-5p." (PMID 25686840, 2015). "Furthermore, the functional studies – include growth curves, cell death, migration assays and in vivo studies – verify the tumor suppressive roles of INTS6 and INTS6P1 in HCC." (PMID 25686840, 2015). "INTS6P1 has never been reported as a tumor suppressive non coding gene in any human cancer." (PMID 25686840, 2015).
cancer (2 papers, 2015 to 2019). A tumor composed of atypical neoplastic, often pleomorphic cells that invade other tissues. "Furthermore, tumors in which INTS6 or INTS6P1 was up-regulated, displayed a lower cross sectional cancer component, when compared to control tumors." (PMID 25686840, 2015).
INTS6P1 also shares sentences with these, for which no sentence is quoted: gastric cancer (1 paper).